CCND1 (cyclin D1)
Diseases named in the same sentence as CCND1 in open-access papers (continued):
Sharing a sentence is not in itself a finding about the gene and the disease.
cancer (continued). "These proteins have been considered pivotal target proteins in various cancers because many anti-cancer drugs can inhibit the expression of cyclin D1 and CDK4." (PMID 27670681, 2016). "Dysregulated phosphorylation of GSK-3β observed in HBP carcinomas in the present study can prevent Thr286 phosphorylation leading to nuclear accumulation of cyclin D1 and cell cycle progression." (PMID 26902162, 2016). "But, as tumors progress to malignant stages (early/late carcinoma), the Cyclin D1 positive cells are observed throughout the solid tumor regions where acini have fused to become a solid sheet of cells." (PMID 27329840, 2016). "Cyclin D1 expressed in about 30% of PTC carcinoma and its overexpression correlate with metastasis of PTC." (PMID 27703281, 2016). "Bcl-2 and Cyclin D1 proteins (P < 0.05) was observed in the majority of cancer cases as compared to those in precancer and adjacent normal controls." (PMID 26581505, 2015). "They show specificity towards Cdk4-cyclin D1 enzyme activity and blocks the growth of cancer cells at the G0/G1 phase." (PMID 25950473, 2015). "Overexpression of cyclin D1 has been reported to shorten the G1 phase and occurs in many types of human cancer, whereas inhibition of its expression blocks G1-S transition." (PMID 26263881, 2015). "The reason behind this is the fact that cancers resistant to PI3K inhibitors present with persistence to cyclin D1 pathway activation as determined by the presence of Rb phosphorylation." (PMID 26059247, 2015). "The protein content analysis showed that UbcH10 knockdown suppressed the expression of Ki67 and cyclin D1, and thus influenced the proliferation and cell cycle in cancer cells." (PMID 25739083, 2015). "Cyclin D1 was one of the traditional oncogenes in the regulation of cancer malignancy, and more recently, was regarded to miRNA genesis and maturation though regulating DICER1, the key enzyme for miRNAs processing 8,20." (PMID 25702703, 2015). "These crucial considerations would anticipate potential drawbacks of the clinical targeting of Cyclin D1 as a therapeutic approach against cancer." (PMID 26503526, 2015). "Previous studies have shown that luminal cancers harbor recurrent amplifications and overexpression of CCND1, whereas basal-like tumors harbor recurrent deletions and down-regulation of it." (PMID 26148869, 2015). "Cyclin D1 (CCND1), c-MYC, and DNA-binding protein inhibitor ID-2 (ID2) genes encode proteins strictly involved in cell proliferation and cancer development." (PMID 26450900, 2015). "The growth of cancer cells in vitro is inhibited by BPT at much lower concentrations than it inhibits the enzyme Cdk4-cyclin D1 in vitro." (PMID 25950473, 2015). "The interaction between retinoid signaling and cyclin D1 has also been reported in a variety of cancer cells." (PMID 25806093, 2015). "Cyclin D1-specific cytotoxic T lymphocytes (CTLs) have been demonstrated in cancer patients with MCL and colorectal cancer." (PMID 25888530, 2015). "The CCND1 is a well-recognized oncogene that is amplified and/or overexpressed in a substantial proportion of human cancers including colon, prostate and breast." (PMID 25818893, 2015). "Cyclin D1 has been established as a potent proto oncogene, and the overexpression of cyclin D1 has been observed frequently in human cancer, including OSCC." (PMID 25645517, 2015). "Recent evidence indicates that deregulation of cyclin D1 is involved in cancer progression including metastasis." (PMID 25971210, 2015).
cancer (continued). "Accumulation of Cyclin D1 leads to cell cycle disregulation favouring cell proliferation and survival as seen in many cancers." (PMID 26491966, 2015). "The Wnt/β-catenin signalling pathway regulates the expression of molecules involved in cancer progression and tissue infiltration such as matrilysin, laminin, and cyclin-D1." (PMID 26399408, 2015). "We show here a novel strategy for the development of recombinant vaccines carrying cyclin D1 cancer antigens that can be targeted to dendritic cells (DCs) via CD40." (PMID 25888530, 2015). "Activated AR is a potent stimulator of cell cycle progression from G1 to S phase in cancer cells through the Cyclin D1/retinoblastoma/E2F1 axis." (PMID 25749045, 2015). "MAPK has been shown to be involved in the induction of cycle related β-catenin and cyclin D1 in many types of cancer." (PMID 26229542, 2015). "Amplifications of cyclin genes are amongst the most common alterations in cancers, with cyclin D1 (CCND1) amplification rates ranging from 15–40%." (PMID 25596748, 2015). "This unique chromatin architecture explains the mechanism by which CCND1 is misregulated in cancers harboring this type of distal chromosomal translocation." (PMID 25799187, 2015). "N3 and TAX also decreased the self-renewal of cancer stem cells, while cyclin D1 increased mammosphere numbers." (PMID 25702703, 2015). "Another oncogenic AS event that sustains uncontrolled proliferation of cancer cells affects the cyclin D1 (CCND1) protooncogene." (PMID 26273627, 2015). "Ten amplified cases showed high-level gene amplification (≥10 CCND1 signals per cancer cell), including 5 cancers (#21, #25, #26, #28, #31) with large CCND1 gene signal clusters." (PMID 25649416, 2015). "Deregulation of the cyclin D1/CDK4/6/Rb pathway leads to increased cell proliferation; this signaling axis is one of the most frequently mutated pathways in cancers." (PMID 26337082, 2015). "It has been reported that cyclin D1 and survivin are downstream targets of Notch1 and collectively play a role in chemoresistance in cancer." (PMID 26011160, 2015). "Amplification or over-expression of Cyclin D1 plays a pivotal role in the development of a subset of human cancers, including those of the breast, liver, retina and esophagus." (PMID 25768009, 2015). "Collectively, these results indicate that expression of NS4B in human hepatocytes induces cancer-related NF-κB target genes including C-myc, Mcl-1, Cyclin D1 and MMP-9 via EOR-Ca2+-ROS-NF-κB pathway." (PMID 25875501, 2015). "Cyclin D1 is frequently overexpressed in human cancer, and it has been proposed as a therapeutic target." (PMID 26431489, 2015). "Alterations in the CCND1 gene affect the cell cycle and are frequently observed in a variety of cancers." (PMID 25436006, 2015). "Previous studies have shown that miR-195 prevents cell proliferation and promotes apoptosis in other cancers by binding to the 3′–UTR of mRNAs of CCND1." (PMID 25823925, 2015). "There are several suggested target genes for miR-193b in different cancers, for example, CCND1, ETS1, and KIT9–16." (PMID 26129688, 2015). "Curcumin also down-regulates the expression of Cyclin D1, the proto-oncogenes that are overexpressed in several types of cancer and plays a crucial role in cell cycle progression and proliferation." (PMID 26464579, 2015). "In total, FISH results on both PTEN deletions and amplifications of HER2, CCND1 and MYC were available in subsets of 1,047 (HER2), 792 (MYC) and 1,149 (CCND1) cancers." (PMID 26672755, 2015). "In cancer cells that have overactive CDK4/6-cyclin D1 activity and a functional Rb protein, CDK4/6 inhibitors block Rb phosphorylation, preventing its deactivation, and leading to G1 cell-cycle arrest or senescence." (PMID 26337082, 2015). "Cyclin D1 is sequestered in the cytoplasm of mammalian cancer cells, where the enforced nuclear localization of cyclin D1 induces apoptosis." (PMID 26620414, 2015).
cancer (continued). "In accordance with these results, our study showed that cyclin D1 and cyclin D2 are also up-regulated in the majority of human primary lung tumors and cancer cell line (A549 and SK-MES-1)." (PMID 26325180, 2015). "The cyclin D1 locus is amplified in more than 30% of cancers, and the cyclin D1 protein is frequently overexpressed in both invasive cancers and pre-invasive lesions of the bronchial epithelia." (PMID 25971210, 2015). "The relevance of the cyclin D1 gene in cancer was apparent upon its identification; this locus had been indicated as involved in a chromosomal rearrangement of benign parathyroid tumors." (PMID 25436006, 2015). "In contrast, PTEN deletion was found in only 12 % of 237 CCND1 amplified cancers, but in 21 % of 912 tumors with normal CCND1 copy numbers (p = 0.0020)." (PMID 26672755, 2015). "Cyclin D1 regulates G1 to S phase progression and its overexpression has been reported in various carcinomas." (PMID 25907675, 2015). "To date, the high expression of cyclin D1 in cancer tissue has been believed to play a role in cell proliferation due to its correlation with Ki-67 expression." (PMID 24944679, 2014). "Cyclin D1 is considered as an oncogene because of its overexpression with high activity in most human cancers." (PMID 24970807, 2014). "While over-expression of ErbB2 or Ras is sufficient to initiate breast cancer in female mice, cancer initiation is completely blocked in Pin1−/− mice, an effect that appears to be mediated via negative regulation of cyclin D1 levels by Pin1." (PMID 24416409, 2014). "Since cell cycle plays a major role in many instances of cancer, we planned to evaluate the expression levels of cyclin D1 which helps in the cell cycle G1/S transition." (PMID 24949454, 2014). "Very few cells were positive for cyclin D1 in normal renal tissue, and cancer cells expressed cyclin D1 at different ratio." (PMID 25322986, 2014). "Cyclin D1, a key regulator of cell cycle progression, is frequently amplified and over-expressed in cancers." (PMID 25170806, 2014). "Next, the effect of intratumoral injection of these recombinant lentiviruses targeting cyclin D1 on attenuation of the growth of pre-existing cancer was assessed." (PMID 24618206, 2014). "Cyclin D1 is often overexpressed in cancers, driving the cell cycle inappropriately and preventing normal G1 arrest." (PMID 25402211, 2014). "miR-18a also reduced mRNA levels of CCND1; CCND1 plays an important role in promoting cell cycle progression, and is frequently overexpressed in cancer, including CRC." (PMID 25379703, 2014). "Seven days after virus injection, there was a significant difference in cancer volume between Virus_Scramble and Virus_CCND1 (P < 0.05)." (PMID 24618206, 2014). "In contrast, the activation and cellular mis-localization of pro-survival and proliferation proteins such as β-catenin, NF-κB, survivin or cyclin D1 have been reported in various types of cancers." (PMID 24429466, 2014). "Several studies mentioned that elevated expression of cyclin D1 or B1 conferred chemoresistance, while decreased expression enhanced the sensitivity of cancer cells to cisplatin." (PMID 25277180, 2014). "Once tumors reached a volume of 80–100 mm3, the cancer was injected with 50 μl of a Saline, Virus_Scramble, or Virus_CCND1." (PMID 24618206, 2014). "Mitotic figure is a marker of proliferation and TUNEL-positive staining is a marker of apoptosis; results from these experiments suggested that silencing of cyclin D1 inhibited cancer cell growth in vivo." (PMID 24618206, 2014). "As key regulators of the G1 progression step within the cell cycle, cyclin D1 have been suspected to play a pivotal role in the process of carcinogenesis and cancer progression." (PMID 24728073, 2014). "In this study, we observed the expression of PRO2000/ANCCA, Ki-67 and Cyclin D1 in series of sections and found these proteins were expressed in same cancer cell nucleus." (PMID 24708861, 2014).
cancer (continued). "In those ER-related cancer cells, E2-activated ERα modulates the expression of key cell cycle regulatory genes, including Cyclin D1 and the transcription factor E2F1." (PMID 25221777, 2014). "Recent studies have suggested that activation of eIF4E is particularly important for the translation of a subset of cancer promoting mRNAs including cyclin D1 and anti-apoptotic proteins." (PMID 24504069, 2014). "Cyclin D1 is one of the most important proteins to regulate cell cycle, and related with the development of many cancers." (PMID 24884417, 2014). "Silencing Cyclin D1 expression by miR-17/20 can induce G1/S cell cycle arrest and inhibit cancer cell proliferation." (PMID 24970807, 2014). "We were interested in how CCL19 and AL10 modulated cyclin D1 expression because this oncoprotein is overexpressed in many cancers and is a potential target for cancer treatment." (PMID 24915301, 2014). "Prior reports have demonstrated in vitro and/or ex vivo inhibition of cyclin D1 protein expression and decreased cell proliferation with antisense single-stranded oligonucleotides or siRNA for cyclin D1 mRNA in various cancer cells." (PMID 25437003, 2014). "Recent studies revealed multiple novel functions of cyclin D1, including cancer stem cell self-renewal, VEGF-stimulated vascularization and chromosomal instability." (PMID 25322986, 2014). "Overexpression of Cyclin D1 plays an important role in several cancers by driving mitotic processes." (PMID 24505380, 2014). "Cyclin D1, an important cell cycle regulator, is frequently overexpressed in several human cancers including breast and cervical." (PMID 24624140, 2014). "Cyclin D1 expression is altered in various cancers, suggesting that its deregulation contributes to tumorigenesis." (PMID 24602161, 2014). "Potential roles of cyclin D1 overexpression have been presumed in various types of cancers, including CRC." (PMID 24728073, 2014). "Many common cancers have CCND1 amplification rates of 15–40%, and higher rates of cyclin D1 mRNA and protein overexpression." (PMID 25437003, 2014). "Inhibition of cyclin D1 expression markedly suppressed cell proliferation and the beginning of S phase in the cell cycle of many cancers." (PMID 24618206, 2014). "It does this, at least in part, by down-regulating PIWILI, cyclin B1, cyclin D1, bcl2 and up-regulating bax gene expression in several types of cancer cells, including A549." (PMID 25007054, 2014). "Cyclin D1 has been extensively investigated in cancer development and is seen as an important regulator of the G1- to S-phase transition in the cell cycle." (PMID 24602161, 2014). "The NCI-N87-derived cancer that was infected with Virus_CCND1 exhibited a 44.7% (P < 0.05) and a 34.9% (P < 0.05) decrease in weight, by comparison with Saline and Virus_Scramble, respectively." (PMID 24618206, 2014). "HEPACAM down-regulation has been reported in several human cancers and is believed to function by down-regulating c-myc and cyclin D1." (PMID 24885874, 2014). "For example, inhibition of cancer cell proliferation and invasion were seen, as well as induction of cell cycle arrest at G1 phase through up-regulation of p27, down-regulation of cyclin D1, and repression of Akt activation." (PMID 24454732, 2014). "In this study, we demonstrate that miR-188 exerts anti-cancer potential via downregulating multiple G1/S related genes, including CCND1, CCND3, CCNE1, CCNA2, CDK2 and CDK4." (PMID 25304455, 2014). "Human CCND1 is located on chromosome 11q13 where DNA rearrangement and amplification have been detected in several types of human cancers including HNSCC." (PMID 25437003, 2014). "Activation of Wnt/β-catenin and Hedgehog/Gli1 signalings results in overexpression of downstream c-Myc and cyclin D1, which are involved in cancer cell proliferation." (PMID 25386960, 2014).
cancer (continued). "Despite the transcriptional activation of the cyclin D1 gene by nuclear β-catenin in normal or cancer cells, the link between β-catenin and cyclin D1 remains complex in HCC." (PMID 24419005, 2014). "Data from several clinical studies indicate that cyclin D1 expression is a biomarker of cancer phenotype and disease progression in several cancers." (PMID 25437003, 2014). "Specifically, we examined sensitivity of cancer cells in the presence of mutations and/or over-expression of BRAF, CDH1, ERBB2, CCND1 and MET." (PMID 24884660, 2014). "For instance, amplification of CCND1 gene or overexpression of Cyclin D1 protein has been found in a wide spectrum of human cancers." (PMID 25304455, 2014). "We have found occupancy of β-catenin on the p68 promoter as well as Cyclin D1 promoter (positive control) by ChIP assay in four different cancer cell lines and relatively more in the case of HCT116 and 4T1." (PMID 25499975, 2014). "The repression of cyclin D1 transcription was a key target of DACH1 in regulating cancer cell proliferation." (PMID 25322986, 2014). "A statistically significant difference in cancer volumes between Saline- and Virus_CCND1-injected cancers was seen as early as five days after the viral injection (P < 0.01)." (PMID 24618206, 2014). "Several known cancer-related genes, such as CCND1, FGF4, FGF3, and CTTN, have been mapped to the 11q13 chromosome region." (PMID 24930674, 2014). "Dysregulation of CCND1 is commonly observed in human cancer, with overexpression of it frequently cited as a potential biomarker." (PMID 25520916, 2014). "It has been documented that some phytochemicals, like curcumin, resveratrol, genistein, and apigenin, can reduce cyclin D1 overexpression in cancer cells." (PMID 24812569, 2014). "Gene amplification and abnormal expression of cyclin D1 have been described in several human cancers." (PMID 25015194, 2014). "Curcumin treatment or knockdown of KLF5 by lentivirus-shKLF5 down-regulated cyclin D1 expression and decreased cancer cell growth." (PMID 25170806, 2014). "For example, overexpression of cyclin D1, an important regulator of the cell cycle, promotes cancer cell proliferation, while deregulated expression of B-cell lymphoma-xl protects cancer cells from apoptosis." (PMID 24533079, 2014). "The results demonstrated that silencing EphB2 promoted cancer growth by stimulating cell proliferation through a mechanism of G1/S phase breakthrough, which was dependent on a cyclin D1/CDK6 cell cycle regulating signal." (PMID 24959213, 2014). "Cyclin D1 was detected in half of the carcinoma tissues and cyclin D3 was observed in only one of the four carcinoma tissues, while cyclin D1 and D3 were slightly detected in normal tissues." (PMID 24765199, 2014). "The combination of the CCND1 11q and 8p regions of amplification has previously been reported to be a characteristic of luminal carcinomas." (PMID 24887297, 2014). "Cyclin D1, cyclin E1 and pRb are known to orchestrate cell cycle progression, and functional interaction between cyclin D1, cyclin E1 and pRb plays an important role in cancer cell growth and tumorigenesis." (PMID 23383003, 2013). "Immunohistochemical staining was performed to observe the expression of cyclin D1 and Ets1 in these cancer specimens." (PMID 23383271, 2013). "Cyclin D1 over-expression in human cancers is elucidated by multiple mechanisms, including genomic alterations, post-transcriptional regulation, and post-translational protein stabilization." (PMID 23383271, 2013). "As downstream target genes of the Wnt/β-catenin signaling pathway, CCND1 and C-MYC encode regulators of cancer cell proliferation, migration and invasion." (PMID 23761839, 2013).